EFNA1 (ephrin A1)
Diseases named in the same sentence as EFNA1 in open-access papers (continued):
Sharing a sentence is not in itself a finding about the gene and the disease.
non-small cell lung carcinoma (4 papers, 2012 to 2023). A group of at least three distinct histological types of lung cancer, including non-small cell squamous cell carcinoma, adenocarcinoma, and large cell carcinoma. "Sukka-Ganesh revealed that EFNA1 could significantly inhibit cell proliferation and tumor formation in non-small cell lung cancer." (PMID 37160815, 2023). "Certain studies show that either treatment with ephrin-A1-Fc or EphA2 knockdown in NSCLC (Non-Small Cell Lung Cancer) cells lowers cell proliferation and migration in vitro mainly through reduced S897 phosphorylation and downregulation of ERK1/2 (Extracellular signal-Regulated Kinase 1/2) activity." (PMID 36142306, 2022).
adenoid cystic carcinoma (3 papers, 2014 to 2025). A malignant tumor arising from the epithelial cells. "A previous study has reported a correlation between EPHA2/EFNA1 expression and perineural and vascular invasion in Adenoid Cystic Carcinoma." (PMID 40075699, 2025). "In another study, EFNA1/EPHA2 was correlated with TNM stage and perineural invasion in adenoid cystic carcinoma of the salivary glands." (PMID 37719704, 2023). "We report a case of adenoid cystic carcinoma with perineural spread and provide the first published evidence that EphA2 expression without ephrin-A1 and epithelial–mesenchymal transition might play important roles in adenoid cystic carcinoma progression." (PMID 24606764, 2014).
colitis (3 papers, 2021 to 2024). Inflammation of the colon. "Previous studies have also reported that exhibits a therapeutic effect in experimental colitis by inhibiting the CEBPB/PCK1 and CEBPB/EFNA1 pathways, which are associated with the PI3K-Akt and P38 MAPK pathways." (PMID 38675921, 2024). "In conclusion, we found that PCK1 and EFNA1 are highly expressed in colitis and they are regulated by CEBPB through two super-enhancers, and we further demonstrate their role in vivo and in vitro." (PMID 35910380, 2022). "The assessment of the changes induced by UniPR1331 and EphA2 on mRNA levels of EphA2 and ephrin-A1 in colitis will contribute to further enrich the scenario." (PMID 34074058, 2021). "To verify whether CEBPB regulates PCK1 and EFNA1 to improve colitis, we designed the interfering RNA of CEBPB." (PMID 35910380, 2022). "In summary, this study shows that inhibition of super-enhancer–driven CEBPB/PCK1 and CEBPB/EFNA1 signaling pathways can reduce LPS-induced barrier dysfunction in vitro and improve DSS-induced experimental colitis in vivo." (PMID 35910380, 2022). "In vivo experiments, nintedanib significantly alleviated DSS-induced colitis in mice by inhibiting CEBPB/PCK1 and CEBPB/EFNA1 signaling pathways." (PMID 35910380, 2022). "In LPS-induced Caco-2 cells, drugs commonly used in clinical colitis including tofacitinib, oxalazine, mesalazine, and sulfasalazine inhibited mRNA levels of CEBPB, PCK1, and EFNA1." (PMID 35910380, 2022).
COVID-19 (3 papers, 2022 to 2025). A disease caused by infection with severe acute respiratory syndrome coronavirus 2. "ICU COVID-19 patients who will eventually die had similar ephrin-A1 and elevated EphA2 levels compared to ICU survivors." (PMID 37175942, 2023). "Although ephrin usage by coronaviruses has not been previously reported in the peer-reviewed literature, a recent abstract reported an upregulation of ephrin A1 and B2 in the saliva of COVID-19 patients." (PMID 35891338, 2022). "A study suggested that ephrin-A1-mediated inflammatory signalling may contribute to COVID-19 disease progression." (PMID 37175942, 2023).
gastric tumor (3 papers, 2020 to 2025). "High levels of GMAN promoted gastric tumor metastasis and adverse survival through the regulation of Ephrin A1 translation." (PMID 32457731, 2020).
glioblastoma (3 papers, 2017 to 2025). The most malignant astrocytic tumor (WHO grade IV). "Transfection with full-length human ephrin A1 into glioblastoma multiforme (GBM) cells exhibits a dramatic suppression of EphA2 and inhibits multiple malignant features, including impaired anchorage-independent growth, proliferation, and migration." (PMID 32811512, 2020).
lymph node metastasis (3 papers, 2021 to 2023). "And EFNA1 expression is associated with lymph node metastasis (P = 0.043), TNM staging (P = 0.021), and degree of invasion (P = 0.024), respectively." (PMID 34399788, 2021). "Clinical data from patients with ESCA were further collected, to analyze the relationship between EFNA1 expression and ESCA clinical parameters, which showed that EFNA1 expression was associated with TNM staging (P = 0.021), lymph node metastasis (P = 0.043), and invasion depth (P = 0.024)." (PMID 34399788, 2021). "It was found that EFNA1 expression was related to clinical factors (TNM staging, P = 0.031; lymph node metastasis, P = 0.043; infiltration, P = 0.016)." (PMID 34399788, 2021).
myocardial infarction (3 papers, 2021 to 2025). Gross necrosis of the myocardium, as a result of interruption of the blood supply to the area, as in coronary thrombosis. "Future applications of these tools will allow us to investigate the dynamic changes in EFNA1 expression profile that occur in pathological states such as myocardial infarction and upon therapeutic treatments." (PMID 40003866, 2025). "Ephrin-A1 expression in the myocardium is decreased following myocardial infarction in mice, and exogenous ephrin-A1 dramatically diminishes tissue injury." (PMID 33511463, 2021). "During a myocardial infarction (MI) event, EFNA1 expression decreases in injured cardiomyocytes." (PMID 40003866, 2025). "EFNA1 (ephrinA1), a highly expressed tyrosine kinase receptor-ligand in healthy cardiomyocytes, is reduced following myocardial infarction (MI)." (PMID 40003866, 2025).
squamous cell carcinoma (3 papers, 2012 to 2025). A carcinoma arising from squamous epithelial cells. "Transcriptome analysis of multiple cancers from the TCGA database also revealed that EFNA1 transcription is tumor specific in CC compared with other squamous cell carcinomas." (PMID 39964764, 2025). "Here we demonstrated that both ephrin-A1 in squamous cell carcinoma cells (SCC-9) and especially soluble ephrin-A1 in the supernatants were up-regulated under hypoxic condition." (PMID 24040255, 2013). "S100A4 induced ephrin-A1 mRNA and protein expression in adenocarcinoma, but not in squamous carcinoma cell lines, whereas the level of osteopontin was unaffected by S100A4 treatment." (PMID 22853000, 2012). "Interestingly, we observed that S100A4 was able to induce expression of ephrin-A1 both at the mRNA and protein level in adenocarcinoma, but not in squamous cell carcinoma cell lines." (PMID 22853000, 2012).
bladder cancer (2 papers, 2018 to 2023). "In bladder cancer, Chu and Zhang showed that EFNA1 could causd the internalization and downregulation of EPHA2 on endothelial cells, leading to the activation of angiogenesis." (PMID 37160815, 2023). "Leflunomide, a common drug for rheumatoid arthritis, has recently been reported to be able to inhibit the angiogenesis and tumor growth in bladder cancer by decreasing the expression of EFNA1." (PMID 37160815, 2023).
cancers of lung (2 papers, 2015 to 2023). "Our study found that the CpG site cg06639488 (EFNA1) to have cross‐cancer effect on breast and lung cancer, consistent with previous findings." (PMID 37449541, 2023).
colon carcinoma (2 papers, 2010 to 2024). "Furthermore, it has been observed that the down-regulation of EFNA1 expression exerts inhibitory effects on the three-dimensional growth of HT29 colon cancer cells." (PMID 38675921, 2024).
diabetes (2 papers, 2020 to 2024). "Plasma ephrin-A1 and VEGF165 levels in fifty-five subjects including 19 individuals without diabetes (non-DM), 16 patients with diabetes (DM) but without diabetic retinopathy, and 20 patients with diabetic retinopathy (DR), were determined by ELISA." (PMID 32758187, 2020). "Secondly, there are no strict restrictions on the types of gastritis control cases, and some diseases that may affect serum EFNA1 and MMP13 levels, such as infection, ischemia, and diabetes, are also not considered." (PMID 38987376, 2024).
ischemia (2 papers, 2024 to 2025). A hypoperfusion of the BLOOD through an organ or tissue caused by a PATHOLOGIC CONSTRICTION or obstruction of its BLOOD VESSELS, or an absence of BLOOD CIRCULATION. "A single intramyocardial injection of chimeric EFNA1-Fc at the time of ischemia mitigates the injury in both reperfused and non-reperfused mouse myocardium by reducing apoptosis, necrosis, and inflammation." (PMID 40003866, 2025). "Previous work from our group has shown that a single intra-myocardial injection of chimeric EFNA1-Fc at the time of ischemia in non-reperfused myocardium lowers cardiomyocyte injury by 50 percent at 4 days post-MI, by reducing necrosis, apoptosis, and inflammatory cell infiltration." (PMID 40003866, 2025).
liver cancer (2 papers, 2021). An epithelial or non-epithelial malignant neoplasm that arises from the liver. "Accumulating evidence indicates that an elevated ephrin-A1 expression is positively correlated with a worse prognosis in some cancers such as colon and liver cancer." (PMID 33804570, 2021).
lung adenocarcinoma (2 papers, 2012 to 2014). A carcinoma that arises from the lung and is characterized by the presence of malignant glandular epithelial cells. "Another study analyzing 11 Ephs and 8 ephrins, indicated that EphA4 and ephrin-A1 gene expression was associated with improved lung adenocarcinoma patients’ outcome, possibly by affecting cancer cell migration and invasion." (PMID 24495444, 2014). "Furthermore, we have demonstrated that S100A4 induces expression of ephrin-A1 in lung adenocarcinoma cell lines, and that the expression of these potential biomarkers is significantly associated in the primary tumor samples." (PMID 22853000, 2012).
medulloblastoma (2 papers, 2024 to 2025). A malignant, invasive embryonal neoplasm arising from the cerebellum. "Stimulation with ephrin-A1 failed to elicit notable phenotypic effects, whereas ephrin-B1 induced modest activation of type A Eph receptors in Uw-402, suggesting cross-reactivity and ligand promiscuity within the Eph/ephrin system in medulloblastoma." (PMID 41200151, 2025). "Furthermore, ephrin-A1 expression appears largely confined to non-SHH medulloblastoma subtypes, with minimal or absent expression in SHH-driven tumors." (PMID 41200151, 2025).
metastatic disease (2 papers, 2021 to 2025). "ADAM12, ephrin-A1, and EphA2-contribute to growth or cell migration in primary and metastatic tumors." (PMID 33946495, 2021). "Finally, we identified the EPHs (EPHA2, EPHA4, EPHA8, and EPHB4) and EFNs (EFNA1, EFNA3, EFNA4, and EFNB2) that are significantly overexpressed in the aggressive epithelioid histological subtype and revealed that the majority of EPHs/EFNs are overexpressed in metastatic disease." (PMID 41516312, 2025).
Parkinson disease (2 papers, 2012 to 2015). A progressive degenerative disorder of the central nervous system characterized by loss of dopamine producing neurons in the substantia nigra and the presence of Lewy bodies in the substantia nigra and locus coeruleus. "Activation of EphA receptor-mediated signals by ephrin-A1 from within the lateral ventricle could potentially be utilized in the treatment of neurodegenerative diseases such as Parkinson’s disease." (PMID 26024354, 2015). "Moreover, the findings provide important molecular evidence supporting ephrin-A1 stimulation of dopaminergic neurogenesis in a rat model of Parkinson’s disease." (PMID 26024354, 2015). "We conclude that activation of EphA receptor–mediated signaling by clustered ephrin-A1-Fc from within the lateral ventricle could potentially be utilized in the treatment of neurodegenerative diseases such as Parkinson's disease." (PMID 22363788, 2012).
rectal cancer (2 papers, 2008 to 2012). A primary or metastatic malignant neoplasm that affects the rectum. "Of them, copy number and mRNA expression of EFNA1 increased from rectal adenoma to carcinoma, and C13orf27 and PMEPA1 with gains in both adenoma and carcinoma were overexpressed in rectal cancer tissues." (PMID 23158542, 2012). "Copy number increase of EFNA1 (1q22), PTGS2 (1q31.1), KDM5B (1q32.1), ESRRG (1q41), KIFC1 (6p21.32), PBX2 (6p21.32) and SOX4 (6p22.3) were only detected in rectal cancer in array CGH." (PMID 23158542, 2012). "In summary, we identified EFNA1 (1q), C13orf27 (13q), PMEPA1 (20q), GPNMB (7q) as candidate driving genes of genomic aberrations in rectal cancer." (PMID 23158542, 2012). "We identified one well known CRC gene (SMAD2) and several other genes (EFNA1, BOP1, TGIF2 and STMN3) that possibly could be used for rectal cancer characterization." (PMID 18959792, 2008). "On basis of integrative analysis this study identified one well known CRC gene (SMAD2) and several other genes (EFNA1, BOP1, TGIF2 and STMN3) that possibly could be used for rectal cancer characterization." (PMID 18959792, 2008).
type 2 diabetes (2 papers, 2023). "Both type 2 diabetes (two at SND1–PAX4 locus and one at GAST locus) and GC (EFNA1, PTGER4 and PSCA loci) shared three significant variants after Bonferroni’s correction (P < 8.6 × 10−6) with PUD or its subtypes." (PMID 38036781, 2023). "Moreover, FURIN, ASGR1, SORT1, TFPI, PGF, F2R, and EFNA1 were also associated with SBP, adiposity, and type 2 diabetes." (PMID 37940228, 2023).
viral infection (2 papers, 2023 to 2024). "Furthermore, the genes EFNA1 and KITLG, which are associated with viral infection, were found in both enriched pathways, suggesting their potential as therapeutic or preventive targets for PDCoV infection." (PMID 38675921, 2024).
adenoma (1 paper, 2012). A neoplasm arising from the epithelium. "Among them, EFNA1 had increased expression in carcinoma compared with adenoma, and KIFC1 had an upward trend but not significant in statistical analysis." (PMID 23158542, 2012).
Age-related cataract (1 paper, 2024). A type of cataract (opacification of the lens) that forms during the course of aging. "Variants in the genes for ephrinA1 (EFNA1) and ephrinA5 (EFNA5), which encode known ligands of EPHA2, have also been associated with age-related cataract but only EFNA1 reached genome-wide significance." (PMID 38927721, 2024).
allergic disease (1 paper, 2025). An immune response that occurs following re-exposure to an innocuous antigen, and that requires the presence of existing antibodies against that antigen. "The activation of EFNA1 and mast cells provides a new target for Ephrin signaling in allergic diseases, highlighting tissue-specific immune modulation." (PMID 40406253, 2025).
bladder exstrophy (1 paper, 2022). Bladder exstrophy (or classic bladder exstrophy; CEB) is a congenital genitourinary malformation belonging to the spectrum of the exstrophy-epispadias complex (EEC) and is characterized by an evaginated bladder plate, epispadias and an anterior defect of the pelvis, pelvic floor and abdominal wall. "Re-sequence of EFNA1 in the investigated classic bladder exstrophy cohort of our study displays an enrichment of rare protein altering variants." (PMID 36352089, 2022).
Cerebral ischemia (1 paper, 2013). Restriction of arterial blood supply to the brain associated with insufficient oxygenation to support the metabolic requirements of the tissue. "It has been shown previously that ephrin-A1-mediated activation of the EphA2 receptor can increase cerebral endothelial cell permeability, an acute outcome of cerebral ischemia known to be detrimental for stroke outcome." (PMID 23308246, 2013). "Complementary findings of upregulated ephrin-A1 and ephrin-A3 ligands and EphA2 receptors in WT brains after stroke, and in primary cortical neurons exposed to GD, probably suggest that activation of EphA2 receptors is important for ephrin-A1/A3 signaling following cerebral ischemia." (PMID 23308246, 2013).
cervical squamous cell carcinoma (1 paper, 2025). A squamous cell carcinoma arising from the cervical epithelium. "Time-dependent ROC analysis evaluated the prognostic accuracy of a three-gene signature (EFNA1, CXCL8, PPP1R14A) for cervical squamous cell carcinoma survival outcomes." (PMID 40406253, 2025). "A prognostic nomogram integrating three molecular markers (EFNA1, CXCL8, PPP1R14A) with clinicopathological parameters (age, TNM stage) was developed to predict 3-/5-/8-year overall survival in cervical squamous cell carcinoma." (PMID 40406253, 2025).
chlamydial infection (1 paper, 2015). "This profile of EphA2 surface display and receptor upregulation induced by chlamydial infection is strikingly different from that observed after Ephrin-A1 stimulation." (PMID 25906164, 2015).
clear cell renal cell carcinoma (1 paper, 2014). "In this study, mRNA and protein expression of the receptors EPHA1 and EPHA2 as well as of their ligand EFNA1 and their prognostic relevance in clear cell renal cell carcinoma was evaluated." (PMID 25025847, 2014).
colon adenocarcinoma (1 paper, 2025). "Additionally, our transcriptomic analysis of tumors with EFNA1-SE revealed EFNA1 upregulation primarily in CC and colon adenocarcinoma, demonstrating a tumor-specific expression pattern." (PMID 39964764, 2025). "Subsequent transcriptome analyses of tumors with an activated EFNA1-SE (detected ratio >1%) revealed that EFNA1 upregulation was predominantly observed in CC and colon adenocarcinoma (COAD) tumors, highlighting a tumor-specific SE-driven activation of EFNA1 in certain cancer types." (PMID 39964764, 2025).
diabetic retinopathy (1 paper, 2020). "We became interested whether ephrin-A1 is expressed in human plasma, and whether the plasma ephrin-A1 expression was altered in diabetic retinopathy patients." (PMID 32758187, 2020). "However, where does the increased ephrin-A1 come from in diabetic retinopathy remains unknown, it may require further studies including multiple systems and organs." (PMID 32758187, 2020).
ductal carcinomas (1 paper, 2011). "We found an inverse correlation between EphA2 and ephrin-A1 protein expression in a significant number of invasive ductal carcinoma samples in lymph node relative to normal breast and ductal carcinomas confined to the breast, which co-express both." (PMID 21935409, 2011). "By contrast, a disproportionate number of metastatic ductal carcinoma samples that were EphA2 positive displayed little or no ephrin-A1 expression." (PMID 21935409, 2011).
gastrointestinal stromal tumor (1 paper, 2024). "Therefore, to further verify the role of EFNA1 combined with MMP13 in the diagnosis of GC, it is necessary to conduct retrospective studies on multi-centers, large samples, and multiple tissue types [such as gastric malt and Gastrointestinal stromal tumors (GIST)]." (PMID 38987376, 2024).
glaucoma (1 paper, 2025). Increased pressure in the eyeball due to obstruction of the outflow of aqueous humor. "Among them, GADD45B, FZD1, EFNA1, LTBP3, and CST3 have been reported to potentially play a role in the development of both AD and glaucoma." (PMID 40988281, 2025).
in situ carcinoma (1 paper, 2025). A malignant epithelial neoplasm which is confined to the epithelial layer without evidence of further tissue invasion. "Subsequent qPCR and IHC findings confirmed that SCNN1A and EFNA1 were highly expressed in both in situ carcinoma and OV-derived exosomes, supporting their potential as reliable biomarkers for OV." (PMID 40787466, 2025).
lung squamous cell carcinoma (1 paper, 2022). "The expression of EFNA1 was high in bladder urothelial carcinoma (BLCA), EFNA2 was highest in stomach adenocarcinoma (STAD), and EFNA3 was highest in lung squamous cell carcinoma (LUSC)." (PMID 35309935, 2022).
malignant glioma (1 paper, 2014). A grade III or grade IV glioma arising from the central nervous system. "In malignant gliomas, patients positive for EPHA2 and negative for EFNA1 protein exhibited the shortest survival compared to other patients." (PMID 25025847, 2014).